SIKE1 (suppressor of IKBKE 1)
Description:
Physiological suppressor of IKK-epsilon and TBK1 that plays an inhibitory role in virus- and TLR3-triggered IRF3. Inhibits TLR3-mediated activation of interferon-stimulated response elements (ISRE) and the IFN-beta promoter. May act by disrupting the interactions of IKBKE or TBK1 with TICAM1/TRIF, IRF3 and RIGI. Does not inhibit NF-kappa-B activation pathways. Associates with the striatin-interacting phosphatase and kinase (STRIPAK) core complex, forming the extended (SIKE1:SLMAP)STRIPAK complex. The (SIKE1:SLMAP)STRIPAK complex dephosphorylates STK3 leading to the inhibition of Hippo signaling and the control of cell growth.
Synonyms: SIKE; FLJ21168
Tractability: PROTAC: ubiquitination databases record sites on it; its protein half-life has been measured.
Gene: Protein-coding gene on chromosome 1 (114,769,479 to 114,780,699, reverse strand). Ensembl gene ENSG00000052723.
Subcellular location: Cytoplasm
Subcellular location (Human Protein Atlas): Focal adhesion sites; Vesicles
Pathways (Reactome):
Disease: SARS-CoV-1 activates/modulates innate immune responses; SARS-CoV-2 activates/modulates innate and adaptive immune responses
Immune System: TRAF3-dependent IRF activation pathway; TRAF6 mediated IRF7 activation
Gene Ontology:
Molecular function: protein binding; protein kinase binding; protein-macromolecule adaptor activity; small GTPase binding
Biological process: negative regulation of hippo signaling
Cellular component: cytoplasm; FAR/SIN/STRIPAK complex; cytosol
Genetic constraint (gnomAD): Loss-of-function variants: 4 observed, 16.81 expected, observed/expected ratio (o/e) 0.24, 90% interval 0.12 to 0.55. The upper end of that interval is the gene's LOEUF score, 0.55, which puts it in group 2 of 6, group 1 being the genes least tolerant of losing a copy. Missense variants: 185 observed, 223.07 expected, observed/expected ratio (o/e) 0.83, 90% interval 0.74 to 0.94. Synonymous variants: 77 observed, 88.01 expected, observed/expected ratio (o/e) 0.87, 90% interval 0.73 to 1.06.
Homologues: Orthologues: chimpanzee SIKE1 (100% identical), macaque SIKE1 (99% identical), dog SIKE1 (98% identical), pig SIKE1 (97% identical), guinea pig SIKE1 (94% identical), mouse Sike1 (92% identical), rat Sike1 (91% identical), rabbit SIKE1 (77% identical), tropical clawed frog sike1 (67% identical), zebrafish sike1 (59% identical), Drosophila melanogaster Fgop2 (29% identical), Caenorhabditis elegans C14B1.8 (25% identical). Paralogues in human: FGFR1OP2 (51% identical).
Diseases named in the same sentence as SIKE1 in open-access papers:
SIKE1 is named in the same sentence as 4 diseases in open-access papers, as found by Europe PMC text mining. Sharing a sentence is not in itself a finding about the gene and the disease. The quoted sentences say what the papers report.
cardiac hypertrophy (6 papers, 2016 to 2024). "SIKE1 was reported to have protective roles in induced cardiac hypertrophy by repressing TBK1-AKT-mTOR cascade." (PMID 39417621, 2024).
SIKE1 also shares sentences with these, for which no sentence is quoted: dilated cardiomyopathy (1 paper); heart failure (1); hypertrophic cardiomyopathy (1).